BRAF (B-Raf proto-oncogene, serine/threonine kinase)
Diseases named in the same sentence as BRAF in open-access papers (continued):
Sharing a sentence is not in itself a finding about the gene and the disease.
tumor (continued). "By causing genomic instability, the BRAF (V600E) mutation may coexist with secondary genetic and/or epigenetic alterations, which in turn might cooperate in terms of tumour aggressiveness and even be more reliable prognostic indicators for PTC." (PMID 30916170, 2019). "A molecular screening of the tumor revealed a BRAF V600E mutation." (PMID 31781502, 2019). "One tumor harbored the BRAF mutation (p.Asp594His mutation)." (PMID 31319569, 2019). "At the same time, drugs have been developed targeting specific mutations, i.e. BRAF (BRAF is a human gene that encodes a protein called B-Raf), resulting in significant responses in tumor regression (set up in this clinical study for 18 months), as well as a higher percentage of long-term survivors." (PMID 30999846, 2019). "We investigated whether the glucose metabolic profiles were correlated with tumor differentiation and BRAF mutations in advanced thyroid cancer as well as PTC." (PMID 31888560, 2019). "Initial treatment with targeted therapy may be favored in patients with a BRAF V600 mutation in the context of a large tumor burden and adverse prognostic factors (including increased LDH) in whom rapid disease control is of paramount importance." (PMID 31921863, 2019). "In the overall population tested for BRAF mutations in both tumor tissue and plasma (n = 405), the kappa coefficient was 0.79 (95% CI: 0.67–0.91), the accuracy was 97.3% (95% CI: 95.2–98.6%), the sensitivity was 76.7% (95% CI: 57.7–90.1%), and the specificity was 98.9% (95% CI: 97.3–99.7%)." (PMID 31319569, 2019). "However, tumours with both BRAF mutation and MITF activation were more sensitive to PLX4720 compared to tumours with BRAF mutation but without MITF activation." (PMID 29950679, 2018). "Interestingly, the frequency of BRAF mutations changed considerably in the various tumor sites: in fact, it markedly increased from the rectum to the ascending colon." (PMID 29652830, 2018). "Therefore, the presence of the BRAF V600E mutation cannot be regarded as specific for any tumour entity." (PMID 29963264, 2018). "Until this issue is clarified in larger series, one should not exclude a patient with an early‐onset CRC from MLH1 constitutional methylation testing based on the detection of a BRAF mutation in the tumor, as is currently common practice when selecting patients for MLH1 germline mutation analysis." (PMID 29341452, 2018). "Of tumours, 71% had a BRAF fusion and 8% had a BRAF V600E mutation." (PMID 28388012, 2018). "All these BRAF mutations promote a constitutive stimulation of cell proliferation and tumor growth." (PMID 30218391, 2018). "First, with DEPO, our analysis of druggability in a given tumor is exclusively based on mutation/drug interactions rather than gene/drug interactions, with variants including both predefined mutations (e.g., BRAF V600E) and categories of mutations (e.g., EGFR exon 19 deletions)." (PMID 30053901, 2018). "Thus, the emergence of RAS/BRAF mutations provided powerful insight into the complexity of tumor foci genotype and gained useful clues for treatment option." (PMID 29643917, 2018).
tumor (continued). "In addition, we observed a high concordance (83%) in BRAF-mutation status between tumor tissue and cfDNA possibly reflecting the advanced disease status and the use of fresh biopsies instead of archival tumor material." (PMID 30220966, 2018). "BRAF mutations were present in 26/347 tumors (7.5%); 21 had the classic p.Val600Glu (p.V600E); 4 had non-V600E mutations; and, 1 tumor had p.Val600Glu and p.Ala598Thr at respective variant allelic frequencies (VAFs) of 16% and 10% in a sample with 50% tumor cell DNA." (PMID 30479693, 2018). "Moreover, EPDR1 hypermethylation was significantly correlated with node negativity and a lower tumor stage as well as with mutations in B-Raf proto-oncogene serine/threonine kinase (BRAF) and human transforming growth factor beta receptor 2 (TGFβR2)." (PMID 30360391, 2018). "One reason for tumor cell survival might be the fact that blocking BRAF/MEK causes premature senescence, a cellular state hard to attack by standard therapy." (PMID 30237393, 2018). "Indeed, we observed that a BRAF-mutated patient tumour, which rapidly developed secondary resistance to dual blockade of MAPK pathway, retained strong WNT pathway dependency." (PMID 29895949, 2018). "The association of this SNP on survival among CRC patients may differ according to dietary vitamin D and calcium intakes and according to tumor BRAF mutation status." (PMID 29409465, 2018). "The same relations were detected in our study with a significant association of the coexistence of BRAF and TERTp mutations with gender, advanced age of patients, T3 and T4 stage of disease, the presence of lymph node metastases, larger tumor size, and infiltration of the tumor capsule." (PMID 30200646, 2018). "However, in some BRAF V600E-mutated indolent neoplasms such as melanocytic nevi and MA, the MAPK cascades are activated as well as that in malignant tumors, but their progression proceeds slowly." (PMID 30111351, 2018). "Oncogene-induced senescence, epigenetic alterations, or kinase-inactive mutation may be associated with the tumor evolution of KRAS- or BRAF-mutated adenocarcinoma." (PMID 29690599, 2018). "In an adjusted proportional hazards model including WHO performance status and levels of ALP, CEA and CRP, an elevated level of serum CA 19-9 was associated with a significant relative reduction in survival (adjusted HR = 4.35 (95% CI 2.89–8.28) in patients with tumours harbouring BRAF mutation." (PMID 29872151, 2018). "Prognostic and tumor monitoring applications may provide a rationale for the detection of RAS/BRAF ctDNA mutations in clinical practice." (PMID 29707525, 2018). "PD-L1 expression was significantly associated with older age (p = 0.04), right sided location (p = 0.004), medullary histology (p < 0.001), G3 tumor grade (p < 0.001), sporadic tumor associated neutrophils (TANs) (p = 0.003), BRAF mutation (p = 0.001), and MSI (p = 0.003)." (PMID 29492219, 2018). "Moreover, hsa-miR-378-5p was negatively associated with BRAF in CRC tissues compared to adjacent non-tumor tissues." (PMID 29930763, 2018). "Interestingly, in CRC patients, the majority of those who have PD-L1 positive tumor carry BRAF mutations along with microsatellite instability, suggesting that the immunosuppressive tumor microenvironment can be induced by BRAF mutations." (PMID 30100909, 2018). "This tumor also harbored one missense mutation in BRAF (T241M)." (PMID 29522538, 2018). "However, BRAF mutations and copy number abnormalities have also been reported in DNETs, complicating the genetic background of these tumours and making consensus difficult." (PMID 29058119, 2018). "Patients with the combination of microsatellite stable (MSS) tumours, BRAF mutation and CIMP positive exhibited the worst prognosis in univariate (log rank P<0.0001) and multivariate analyses (hazard ratio 1.75, 95% CI 1.05–2.93, P = 0.03) after adjusting for age, sex, chemotherapy, and TNM stage." (PMID 30188916, 2018).
tumor (continued). "Similarly, the Atg7 deficiency in mice with BRAF-induced lung tumor also resulted in accumulation of dysfunctional mitochondria ultimately leading to tumor growth restriction." (PMID 29643976, 2018). "Furthermore, we observed that tumours with both BRAF mutation and MITF activation were more sensitive to BRAF inhibitors compared to tumours with BRAF mutation without MITF activation." (PMID 29950679, 2018). "Furthermore, 2 of 4 patients who developed ovarian metastases after undergoing curative resections of primary tumours presented the BRAF V600E mutation in primary tumours." (PMID 29662660, 2018). "In a murine model of ATC, the synergistic effect of combining anti-PD1 immunotherapy with BRAF inhibitor therapy has been shown to produce a significant tumor regression as the tumor cells bearing the BRAF V600E mutation tend to bear a higher expression of PD-L1." (PMID 29996921, 2018). "The BRAF V600E mutation alone was significantly associated with more advanced age of the patients (p = 0.024), larger tumor size (p < 0.0001), more advanced disease stage (p = 0.002), and infiltration of the tumor capsule (p = 0.0007)." (PMID 30200646, 2018). "For example, BRAF was mutated in all tumor, spheroid, and LNM samples of patient 2 (pt." (PMID 29130628, 2018). "In particular, they observed a statistically significant greater burden of missense mutations among men, even after adjusting for age at diagnosis, primary tumor site, stage at diagnosis, site of sequenced tumor, history of neoadjuvant treatment, and BRAF and NRAS mutation status." (PMID 29371600, 2018). "We suspect that if mutated BRaf is expressed first, then a critical but unknown pathway is also activated, preventing Grm1 -induced neoplasia." (PMID 29464040, 2018). "Thus, in agreement with the literature, we found that the expression of PD-L1 on NCs is significantly associated with older age, right sided location, medullary histology, G3 tumor grade, BRAF mutation, and MSI status." (PMID 29492219, 2018). "Oncogene-induced senescence appears to decrease the frequency of the multistep progression in KRAS- or BRAF-mutated adenocarcinoma, whose tumor evolution may be associated with epigenetic alterations and kinase-inactive mutations." (PMID 29690599, 2018). "For patients whose tumor harbors a BRAF V600E/K mutation, combination dabrafenib/trametinib may be preferred over immunotherapy since the impact of adjuvant checkpoint inhibitors on the management of subsequent disease progression is not known." (PMID 29848375, 2018). "In addition, tumor size in BRAF wild-type cases ranged from 2 to 5.5 cm (median = 2.2); this value was also less than that in BRAF V600E-mutated patients (p < 0.05)." (PMID 30111351, 2018). "The investigators speculated that BRAF mutations may arise spontaneously in the secondary tumor from a BRAF WT primary tumor." (PMID 29148538, 2018). "Further investigation of the CTH gene in colorectal carcinogenesis with regards to KRAS and BRAF mutations or other molecular characteristics of the tumor may be warranted." (PMID 29694444, 2018). "Selumetinib (a selective MEK inhibitor) and dabrafenib (a selective BRAF inhibitor used in BRAF-mutated tumors) have been shown to increase RAI uptake by RAI-refractory tumor tissues, and these encouraging results are now under investigation (NCT02393690 and NCT03244956)." (PMID 29399330, 2018). "Recently, it was suggested that glioneuronal tumours can be separated into two groups: one group enriched for BRAF mutations with an astrocytic expression phenotype and one group enriched for FGFR1 mutations with an oligodendrocyte precursor expression phenotype." (PMID 29963264, 2018).
tumor (continued). "However, lower frequency of HER2/BRAF/PIK3CA mutations was observed in biopsy samples with <20% tumor cellularity as compared to those with ≥20% tumor cellularity." (PMID 29518290, 2018). "The results of this study contribute to a greater understanding of disease biology among tumours harbouring these somatic mutations and suggest that BRAF/NRAS mutant tumours may be more potent drivers of aggressive tumour biology." (PMID 29755118, 2018). "We additionally evaluated the potential influence of this SNP according to dietary vitamin D, calcium, milk, and total dairy product intake and whether associations varied by tumor microsatellite instability (MSI) or BRAF Val600Glu mutation status." (PMID 29409465, 2018). "In total, 57 (18.9%) tumours harboured BRAF mutations and 245 (81.1%) were the wild-type." (PMID 29479053, 2017). "He made the case for treating BRAF melanomas that have acquired MEK resistance with histone deacetylases—the metabolic compensation of tumour cells leaves them uniquely susceptible to the toxic levels of reactive oxygen species generated, whereas healthy host tissue remains intact." (PMID 29062388, 2017). "Moreover, we compared different tumor stages and found that BRAF mutations were also associated with poorer DFS and OS in both stage I and stage II/III subgroups." (PMID 28583095, 2017). "In accordance to tumor genotyping, the BRAF V600E mutation was found in the basal cfDNA of patient 9 (0.07% of plasma DNA fragments), patient 12 (10.47%), patient 17 (0.40%) and patient 18 (3.64%), and the PIK3CA H1047R mutation was found in the cfDNA of patient 18 (2.62%)." (PMID 27852040, 2017). "The same applied to BRAF mutation in serum and pMMR in tumor." (PMID 28378527, 2017). "BRAF mutation status was determined in available tumour tissue from 54 of the 77 enroled patients." (PMID 28103611, 2017). "Most studies indicated a significant association between BRAF mutation and other factors of poor prognosis such as older age, male gender, higher tumor staging, tumor size, extrathyroidal extension, lymph node metastases, even distant metastases, and recurrence." (PMID 28829399, 2017). "Indeed, tumour cells with BRAF mutations are addicted to ERK1/2 signalling for repression of BIM 58 and pharmacological inhibition of ERK1/2 signalling induces strong increases in BIM expression in many contexts." (PMID 28548464, 2017). "The study included 3063 patients with a low prevalence of dMMR (5%) and BRAF mutation (8.2%) in the whole studied population, however in patients with dMMR tumours, impaired BRAF was noted more often than in proficient MMR (pMMR) tumours (34.6% vs. 6.8% respectively, p < 0.001)." (PMID 28067827, 2017). "In addition to this, BRAF mutations also have a poor prognosis associated with lower survival rates, especially in those tumours with microsatellite instability." (PMID 28106826, 2017). "There were three pairs of genes that were mutated in a mutually exclusive pattern in tumor samples (n = 412): BRAF and NRAS mutations (Bonferroni adjusted p-value < 0.05), BRAF and NF1 mutations (Bonferroni adjusted p-value < 0.05), and NRAS and PTEN mutations (Bonferroni adjusted p-value < 0.05)." (PMID 29383127, 2017). "Indeed, BRAF V600E mutations are observed in 22 of the 45 (49%) MSI-H COAD tumours, but only 4 (2%) frameshift MSI events are observed within the gene." (PMID 28585546, 2017). "The majority of BRAF mutated CRC showed high levels of active EGFR compared to other tumour types." (PMID 28282860, 2017). "A recent retrospective analysis of data from the TRIBE trial suggested that tumor mutations in both BRAF and RAS genes predicted a poor outcome for patients undergoing first-line treatment with Bmab plus FOLFIRI or FOLFOXIRI, although RAS mutations had less impact than BRAF mutations." (PMID 28068936, 2017).
tumor (continued). "In accordance to earlier studies the BRAF-V600E mutation was frequent (20 out of 41 samples; 49%) in the tumour samples predominantly in the mandible region, whilst the SMO-L412F mutation was detected in two (5%) of the tumour samples only, exclusively in the maxilla region." (PMID 27965463, 2017). "Additionally, the subgroup of patients with BRAF mutation in serum and pMMR in tumor was small (n = 14)." (PMID 28378527, 2017). "It remains unclear, however, whether the primary tumour BRAF mutation status is retained in metastases and we are unable to add anything more to this debate, in this study." (PMID 29120401, 2017). "Additionally, some other factors, such as different study design (prospective versus retrospective), tumor KRAS/BRAF/PIK3CA mutation status that affected the survival of CRC patients should also be attributed to some of the heterogeneity." (PMID 28977964, 2017). "Supporting these findings, a previous report showed that stages II and III CRC patients with good prognosis could be categorized into a subtype highly similar to group 2, with features such as MSI, BRAF mutations, and right-sided tumor location." (PMID 28455965, 2017). "Therefore, if progressive disease occurs after a period of tumor response, it is likely that an increase of ctDNA levels with the same primary BRAF mutation as that of the relapsing tumor cells will be detected." (PMID 28484715, 2017). "It is generally accepted that tumor location has a role in the prognostic impact of BRAF mutations." (PMID 28378527, 2017). "However, those with concurrent HT show an alien correlation that tumor with BRAF mutation tends to be solid on US." (PMID 28687736, 2017). "Strategies to manage the aggressiveness of BRAF-mutated tumor is challenging." (PMID 29037218, 2017). "In summary, we showed that PLGG tumorigenicity was low despite the presence of putative CSCs, and our data supported GFAP−/Vimentin+ cells, CDKN2A homozygous deletion in trisomy chromosome 9 cells, and BRAF V600E mutation as candidate drivers of tumor progression in the PXA xenografts." (PMID 29152094, 2017). "A BRAF mutation is diagnosed in approximately 5%–15% of all CRC tumours and is considered a prognostic biomarker of less favourable outcome in the general population of CRC patients overall but also in dMMR subgroup—both in the early stage and advanced disease." (PMID 28067827, 2017). "The concomitant occurrence of KRAS and BRAF mutations is very rare in CRCs (< 1%), which imply tha they may play a role in different tumor subtypes." (PMID 28583095, 2017). "As number of studies showed that BRAF inhibition increased the number of intratumoral cytotoxic T cells and increased expression of tumor-associated antigens on tumor cells, it was hypothesized that BRAF inhibition could synergize with CTLA-4 blockade." (PMID 27075584, 2016). "Notably, these BRAF-mutated tumor cells express the NKG2D ligands MICA/B at a higher level than unmutated tumors as a consequence of the activation of the MAPK pathway." (PMID 27563819, 2016). "Interestingly, in our series 3/4 EGFR mutant patients with progressive disease after EGFR TKI treatment had coexisting mutations in KRAS or BRAF in the primary tumor, in two cases at an allelic frequency higher than EGFR mutations." (PMID 27448974, 2016). "Large-scale study involving 1404 patients with stage II and III CRC demonstrated the association of BRAF mutations with the female gender, localization of tumor in the right side, older age (60 years or more), a high grade of anaplasia, and microsatellite instability." (PMID 27276710, 2016). "BRAF mutations lead to constitutive activation of the MAPK signaling pathway involved in different mechanisms of tumor progression including evasion of apoptosis, unchecked cell replication, neoangiogenesis, tissue invasion, metastasis as well as escape from immune response." (PMID 27563819, 2016).